ZC3H3 (zinc finger CCCH-type containing 3)
Description:
Required for the export of polyadenylated mRNAs from the nucleus. Enhances ACVR1B-induced SMAD-dependent transcription. Binds to single-stranded DNA but not to double-stranded DNA in vitro. Involved in RNA cleavage (By similarity).
Synonyms: KIAA0150; SMICL; ZC3HDC3
Tractability: PROTAC: ubiquitination databases record sites on it.
Gene: Protein-coding gene on chromosome 8 (143,437,655 to 143,541,455, reverse strand). Ensembl gene ENSG00000014164.
Subcellular location: Nucleus
Subcellular location (Human Protein Atlas): Nucleoplasm
Pathways (Reactome):
Metabolism of RNA: Nuclear RNA decay
Gene Ontology:
Molecular function: metal ion binding; R-SMAD binding; SMAD binding
Biological process: RNA catabolic process
Cellular component: nucleus; nucleoplasm; mRNA cleavage and polyadenylation specificity factor complex
Genetic constraint (gnomAD): Loss-of-function variants: 36 observed, 72.25 expected, observed/expected ratio (o/e) 0.5, 90% interval 0.38 to 0.66. The upper end of that interval is the gene's LOEUF score, 0.66, which puts it in group 2 of 6, group 1 being the genes least tolerant of losing a copy. Missense variants: 1,331 observed, 1,269 expected, observed/expected ratio (o/e) 1.05, 90% interval 1 to 1.1. Synonymous variants: 626 observed, 533.72 expected, observed/expected ratio (o/e) 1.17, 90% interval 1.1 to 1.25.
Homologues: Orthologues: chimpanzee ZC3H3 (98% identical), macaque ZC3H3 (83% identical), dog ZC3H3 (77% identical), guinea pig ZC3H3 (74% identical), pig ZC3H3 (72% identical), mouse Zc3h3 (71% identical), rat Zc3h3 (70% identical), tropical clawed frog zc3h3 (32% identical), zebrafish zc3h3 (31% identical), Drosophila melanogaster ZC3H3 (17% identical). Paralogues in human: CPSF4 (8% identical), CPSF4L (6% identical).
Diseases named in the same sentence as ZC3H3 in open-access papers:
ZC3H3 is named in the same sentence as 11 diseases in open-access papers, as found by Europe PMC text mining. Sharing a sentence is not in itself a finding about the gene and the disease. The quoted sentences say what the papers report.
acne vulgaris (1 paper, 2024). "The biological annotation analysis indicates that we have identified 3 pairs of associated genes between gut microbiota and acne vulgaris, including PLA2G4A/FADS2, TIMP3/ADAMTS9 and ZC3H3/CPSF4L." (PMID 38371936, 2024). "After conducting biological annotation, we identified six genes (PLA2G4A, FADS2, TIMP17, ADAMTS9, ZC3H3, and CPSF4L) that may be associated with the pathogenic gut microbiota of acne vulgaris patients." (PMID 38371936, 2024).
adrenocortical carcinoma (1 paper, 2023). "ZC3H3, methylated gene, was regarded to be involved in the regulation of mRNA polyadenylation and can act as risk indicator for predicting prognosis in bladder cancer and adrenocortical carcinoma." (PMID 37189064, 2023).
alcoholic cirrhosis (1 paper, 2024). "Hypermethylated DMRs observed in alcoholic cirrhosis and alcoholic HCC were found in forkhead box K1 (FOXK1), zinc finger CCCH-type containing 3 (ZC3H3), nuclear factor IX (NFIX), histone deacetylase 4 (HDAC4), and tetraspanin 9 (TSPAN9) genes." (PMID 38302914, 2024).
breast carcinoma (1 paper, 2022). "In addition, the genes flanking either orientation, the ZC3H3 and DGAT1, were upregulated in breast cancer." (PMID 36497066, 2022).
Cirrhosis (1 paper, 2024). A chronic disorder of the liver in which liver tissue becomes scarred and is partially replaced by regenerative nodules and fibrotic tissue resulting in loss of liver function. "Changes in the methylation and transcriptional levels of ZBTB38, ZC3H3, FOXK1, and KAZN are important for the development of fibrosis and HCC; and are therefore potential therapeutic targets and diagnostic tools for cirrhosis and HCC." (PMID 38302914, 2024).
Obesity (1 paper, 2024). Accumulation of substantial excess body fat. "Some studies have found that ZC3H3 is involved in mediating nuclear RNA decay, and CPSF4L may be associated with obesity." (PMID 38371936, 2024).
tumor (2 papers, 2022 to 2024). "Many of the m6A regulators have a high SNV mutation frequency in most tumor types, especially in UCEC, SKCM, COAD, and STAD, furthermore, ZC3H3 in UCEC and PRRC2A in SKCM are the top two whose mutation frequency is above 50%." (PMID 39457524, 2024). "Therefore, alterations of ZC3H3 expression may affect the post-transcriptional regulation of various tumor-related genes." (PMID 36471401, 2022).
ZC3H3 also shares sentences with these, for which no sentence is quoted: alcoholism (1 paper); bladder cancer (1); cancer (1); liver disease (1).